MSRA (methionine sulfoxide reductase A)
Description:
[Isoform 1]: Catalyzes the reversible oxidation-reduction of methionine sulfoxide in proteins to methionine. Has an important function as a repair enzyme for proteins that have been inactivated by oxidation. Plays a crucial role in repairing oxidized methionine residues in key lens proteins, such as alpha-crystallin (CRYAA/CRYAB) and cytochrome c (CYCS), thereby restoring their function and maintaining lens transparency (By similarity).
Synonyms: PMSR
Tractability: PROTAC: ubiquitination databases record sites on it; its protein half-life has been measured.
Gene: Protein-coding gene on chromosome 8 (10,054,278 to 10,428,897, forward strand). Ensembl gene ENSG00000175806.
Subcellular location: Mitochondrion (Isoform 1); Mitochondrion matrix; Cytoplasm; Cytoplasm (Isoform 2); Cytoplasm (Isoform 3); Nucleus; Cytoplasm (Isoform 5); Membrane
Subcellular location (Human Protein Atlas): Cytosol; Nucleoplasm
Pathways (Reactome):
Metabolism of proteins: Protein repair
Gene Ontology:
Molecular function: L-methionine (S)-S-oxide reductase activity; peptide-methionine (S)-S-oxide reductase activity; protein binding
Biological process: protein repair; response to oxidative stress
Cellular component: cytoplasm; cytosol; extracellular exosome; mitochondrial matrix; mitochondrion; nucleoplasm; nucleus; membrane
Genetic constraint (gnomAD): Loss-of-function variants: 49 observed, 26.14 expected, observed/expected ratio (o/e) 1.87, 90% interval 1.44 to 1.98. The synonymous counts are far from expectation, so gnomAD's model fits this gene poorly and the ratio says little. Missense variants: 474 observed, 278.55 expected, observed/expected ratio (o/e) 1.7, 90% interval 1.58 to 1.84. Synonymous variants: 160 observed, 108.61 expected, observed/expected ratio (o/e) 1.47, 90% interval 1.29 to 1.68.
Homologues: Orthologues: chimpanzee MSRA (99% identical), rabbit MSRA (89% identical), dog MSRA (87% identical), guinea pig MSRA (86% identical), mouse Msra (86% identical), rat Msra (85% identical), pig MSRA (84% identical), tropical clawed frog msra (56% identical), Drosophila melanogaster MsrA (30% identical), Caenorhabditis elegans msra-1 (24% identical). Paralogues in human: MSRB3 (15% identical), MSRB2 (12% identical), MSRB1 (8% identical).
Diseases named in the same sentence as MSRA in open-access papers:
MSRA is named in the same sentence as 73 diseases in open-access papers, as found by Europe PMC text mining. Sharing a sentence is not in itself a finding about the gene and the disease. The quoted sentences say what the papers report.
Obesity (13 papers, 2010 to 2025). Accumulation of substantial excess body fat. "Of interest are the variants in/near five genes (PTER, NPC1, MAF, SDCCAG8 and TNKS/MSRA) that had previously been associated with obesity also using samples of individuals who were extremely overweight." (PMID 21935397, 2011). "We have previously shown that MsrA plays a role in the metabolic response to diet-induced obesity in mice." (PMID 35332198, 2022). "Nineteen loci have been identified and five of them only are associated with BMI / obesity (FTO, MC4R,NRXN3, TFAP2B, MSRA)." (PMID 22043164, 2011). "The results of this study suggest that polymorphisms of the MC4R, PPARGC1A, MSRA, and TFAP2B genes may be associated with obesity-related traits in a sample of Portuguese children." (PMID 36499740, 2022). "The goals of this study were to test whether increasing the expression of MsrA in mice can protect against obesity-induced metabolic dysfunction and to elucidate the potential underlying mechanisms." (PMID 26448611, 2015). "In this study, we identified that mitochondrial MsrA protects against obesity-induced metabolic dysfunction, further highlighting the importance of mitochondria in the regulation of glucose metabolism under metabolic stress and identifying a novel role for MsrA in this process." (PMID 26448611, 2015). "In addition, both genetic and diet-induced obesity in rats promotes a significant reduction of MsrA activity in visceral adipose tissue." (PMID 26448611, 2015). "Nine loci have been associated with extreme obesity at the genome-wide level, five of them influencing BMI / waist circumference as well as risk for extreme obesity (FTO, MC4R, TMEM18, MSRA, NPC1), four loci being more specific of genetic risk for extreme obesity (MAF, PTER, PRL, SDCCAG8)." (PMID 22043164, 2011). "We first considered that increased MsrA may reduce levels of obesity-induced oxidative stress." (PMID 26448611, 2015). "However, the variants we detected were too infrequent for meaningful obesity association analysis (SDCCAG8 [Thr398Met], TNKS [Pro275Ala], MSRA [Arg6GlufsX88], [Asp142Tyr], [Gly187Ser]) or showed no obesity association (SDCCAG8 [Glu378Asp], TNKS [Gly237Ala]; MSRA [Thr88Met],)." (PMID 26828654, 2016). "TgMito MsrA, but not TgCyto MsrA, mice remain insulin sensitive after high fat feeding, though these mice are not protected from obesity." (PMID 26448611, 2015). "We previously identified that mice lacking the protein oxidation repair enzyme methionine sulfoxide reductase A (MsrA) are particularly prone to obesity-induced insulin resistance suggesting an unrecognized role for this protein in metabolic regulation." (PMID 26448611, 2015). "The lack of the repair of these adducts in MsrA KO mice contributes to their sensitivity to obesity-induced insulin resistance." (PMID 26448611, 2015). "However, analyses were made without adjusting for multiple testing, and further studies are needed to elucidate the involvement of LYPLAL1, NRXN3, MSRA, and TFAP2B in the pathophysiology of obesity." (PMID 21674055, 2011). "However, analyses were made without adjusting for multiple testing, and further studies are needed to confirm the putative role of LYPLAL1, NRXN3, MSRA, and TFAP2B in the pathophysiology of obesity." (PMID 21674055, 2011). "However, our data suggest that increased mitochondrial MsrA can alter metabolic homeostasis under diet-induced obesity by activating AMPK signaling, thereby defining a potential mechanism by which this genetic alteration can prevent insulin resistance without affecting obesity." (PMID 26448611, 2015).
Alzheimer disease (11 papers, 2009 to 2024). A progressive, neurodegenerative disease characterized by loss of function and death of nerve cells in several areas of the brain leading to loss of cognitive function such as memory and language. "For example, MsrA KO mice exhibit many of the neuropathological traits associated with Alzheimer’s disease (AD) and Parkinson’s disease (PD)." (PMID 32456285, 2020). "Interestingly, the expression and activity of MsrA is reduced in brain tissue from aging human patients, and this age-dependent reduction in MsrA activity is linked with the development of Alzheimer’s disease." (PMID 24765077, 2014). "For example, when MsrA is depleted in Alzheimer’s disease (AD) model mice, the level of amyloid-beta (Aβ) significantly increases, indicating that MsrA can directly regulate the oxidation state of Aβ and transform soluble Aβ into aggregated Aβ." (PMID 33806413, 2021). "Studies have shown that MsrA activity was significantly reduced in the brains of Alzheimer’s disease patients and in the cardiomyocytes in cardiac ischemia models." (PMID 26410585, 2015). "While it has been shown that oxidized proteins accumulate in tissues from patients exhibiting age-related diseases such as Alzheimer’s, Parkinson’s, and Huntington’s diseases, and cataracts, reduced MsrA activity was found in the brains of Alzheimer’s disease patients." (PMID 30545068, 2018). "In addition, in old rats and in the brains of patients with Alzheimer’s disease there were decreases in MsrA activity that consequently lead to accumulations of carbonyl adducts in proteins." (PMID 27447933, 2016). "Methionine oxidation in Met-35 of amyloid ß-peptide (Aβ peptide) is thought to be critical for aggregation and neurotoxicity and it was shown that the absence of MsrA modifies Aβ solubility properties and causes mitochondrial dysfunction in a mouse model of Alzheimer’s disease." (PMID 30545068, 2018). "Two of these genes, NEIL2 and MSRA, are related to repair of oxidative damage, and CTSB has been suggested to play a role in Alzheimer's disease." (PMID 20011547, 2009).
breast carcinoma (5 papers, 2007 to 2021). "And a down-regulation of Methionine Sulfoxide Reductase A (MSRA) has been previously linked to a more aggressive phenotype in breast cancer." (PMID 27341628, 2016). "Several of these genes have been previously linked to tumourigenesis in breast cancer, including KDM5B, RAD21, BIRC5, AURKA and MSRA." (PMID 27341628, 2016). "MSRA (methionine sulfoxide reductase A), which acts as ROS scavenger protecting proteins from oxidation, was found downregulated in metastatic hepatocellular carcinoma and breast cancer." (PMID 27206673, 2016). "Comparable levels of MsrA transcript were detected in both the breast cancer cells tested." (PMID 17519015, 2007).
atherosclerosis (4 papers, 2015 to 2025). A disease characterized by the build-up of fatty material and calcium deposition in the arterial wall resulting in partial or complete occlusion of the arterial lumen. "In this study, we examined the impact of hepatic MsrA overexpression on lipid metabolism and atherosclerosis in apoE-deficient (apoE−/−) mice." (PMID 26318157, 2015). "Moreover, we will attempt to reveal the mechanisms underlying the role of acacetin in the MsrA‐ and Nrf2‐related pathways, aiming to provide evidence of its potential therapeutic role in atherosclerosis‐related CVD." (PMID 33241629, 2021). "We hypothesized that hepatic expression of MsrA might attenuate the progression of atherosclerosis by regulating redox state and some key proteins involved in lipid metabolism and inflammation." (PMID 26318157, 2015). "The aim of this study is to investigate whether MsrA with PEP-1, a cell penetrating peptide, fused to its N-terminus can protect against oxidative stress in macrophages and can attenuate atherosclerosis in apolipoprotein E deficient (apoE−/−) mice." (PMID 26410585, 2015). "We found that injection of PEP-1-MsrA could significantly reduce the size of atherosclerotic lesions without altering plasma lipid levels, but injection of MsrA did not affect atherosclerosis." (PMID 26410585, 2015). "However, whether or not MsrA could be used as a therapeutic agent for atherosclerosis has not been investigated." (PMID 26410585, 2015).
dementia (4 papers, 2016 to 2024). Loss of intellectual abilities interfering with an individual's social and occupational functions. "In conclusion, CACNA1C, GABBR2, SCN2A, CTSH, MSRA, and SH3PXD2A may be associated with the neuro-progression of bipolar disorder to dementia." (PMID 39228919, 2024). "In conclusion, the genes CACNA1C, GABBR2, SCN2A, CTSH, MSRA, and SH3PXD2A may be associated with the neuro-progression of bipolar disorder to dementia." (PMID 39228919, 2024). "The results showed that the genes CACNA1C, GABBR2, SCN2A, CTSH, MSRA, and SH3PXD2A were overlapping between patients with bipolar disorder and dementia." (PMID 39228919, 2024). "According to GWAS, the CACNA1C, GABBR2, SCN2A, CTSH, MSRA, and SH3PXD2A genes were common between bipolar disorder and dementia." (PMID 39228919, 2024).
myocardial infarction (4 papers, 2013 to 2020). Gross necrosis of the myocardium, as a result of interruption of the blood supply to the area, as in coronary thrombosis. "CaMKII oxidation could be reversed by methionine sulfoxide reductase A (MsrA) and MsrA knockout mice show exaggerated CaMKII oxidation causing myocardial apoptosis, impaired cardiac function, and an increased mortality after myocardial infarction." (PMID 23423152, 2013). "CaMKII oxidation is reversed by methionine sulfoxide reductase A (MsrA), and MsrA−/− mice show exaggerated CaMKII oxidation and myocardial apoptosis, impaired cardiac function, and increased mortality after myocardial infarction." (PMID 32509147, 2020). "A MsrA (methionine sulfoxide reductase) knockout with higher levels of ox-CaMKII was showing dramatically reduced survival 30 days after myocardial infarction whereas MsrA overexpression seemed to be cardioprotective." (PMID 26379551, 2015). "CAMKII oxidation is significantly increased in the hearts of MsrA KO mice and leads to increased apoptosis and reduced survival following myocardial infarct surgery." (PMID 26448611, 2015).
schizophrenia (4 papers, 2017 to 2023). A major psychotic disorder characterized by abnormalities in the perception or expression of reality. "Several other genes in this region show suggestive evidence of differential expression/splicing in ASD, including MSRA, which has been previously associated with schizophrenia, MFHAS1, and PINX1." (PMID 31230729, 2019).
cataract (2 papers, 2015 to 2021). Partial or complete opacity of the crystalline lens of one or both eyes that decreases visual acuity and eventually results in blindness. "In hyperbaric oxygen conditions, the cytochrome C in the lens of MsrA deficiency mice is readily oxidized at Met-65 and Met-80 residues, leading to the aggregation and decomposition of cytochrome C, and eventually the development of cataracts." (PMID 33806413, 2021).
coronary artery disease (2 papers, 2015). "Recent studies have shown that a single polymorphism, rs10903323 G/A, in the human MsrA (hMsrA) gene is associated with an increased risk of coronary artery disease, highlighting the importance of MsrA." (PMID 26318157, 2015).
Hypertension (2 papers, 2022 to 2025). The presence of chronic increased pressure in the systemic arterial system. "Six genes (PTGS2, TBXA2R, ZNF101, KCNJ2, MSRA, and CMTM5) have been reported to be associated with hypertension." (PMID 39854379, 2025).
Insulin resistance (2 papers, 2015 to 2016). Increased resistance towards insulin, that is, diminished effectiveness of insulin in reducing blood glucose levels. "However, our findings here show that replacing MsrA at high levels in the mitochondria alone abolishes the increased susceptibility to insulin resistance of MsrA KO mice." (PMID 26448611, 2015). "The association between MsrA and insulin resistance might simply reflect alterations in the cells ability to utilize this “last-chance” antioxidant defense system for proteins." (PMID 26448611, 2015). "We recently showed that the lack of MsrA in mice (MsrA KO) directly impairs the regulation of glucose metabolism in that MsrA KO mice are strikingly more susceptible to high fat diet-induced insulin resistance, at least in part by regulating accumulation of oxidative damage." (PMID 26448611, 2015).
liver cancer (2 papers, 2021 to 2023). An epithelial or non-epithelial malignant neoplasm that arises from the liver. "We focused our siRNA screen on cell migration and thereby confirmed a metastasis suppressive role for MSRA, NAT1, PPP2CB, and DLC1 in liver cancer." (PMID 38134284, 2023). "Then, we also explored the correlation between the expression of 11 ROS-related genes and TNM stages in liver cancer, and the findings showed that the expression of CDKN2D, G6PD, MSRA, OXSR1, PFKP, and STK25 was connected with TNM stages (P < 0.05)." (PMID 34795841, 2021).
neuroblastoma (2 papers, 2017 to 2024). Neuroblastoma (NB) is the most common solid, extracranial childhood tumor. "Indeed, pretreatment of human neuroblastoma IMR-32 cells with punicalagin at a dose of 20 μM increased the enzymatic activity of Methionine sulfoxide reductase A (MsrA)." (PMID 39275022, 2024). "In a study that assessed the involvement of MsrA, SIRT1 and RVT in PD, Wu and collaborators demonstrated that phytoalexin was able to enhance the resistance of human neuroblastoma SH-SY5Y cells to 1-methyl-4-phenylpyridinium ion (MPP+)-induced neurotoxicity and that it upregulates MsrA expression." (PMID 29104258, 2017).
adenovirus infection (1 paper, 2019). "At 24 h after adenovirus infection of cultured rat pancreatic stellate cells, MsrA, B1 or B2 expression levels were all conspicuously elevated as confirmed by RT-PCR, Western blot and immunocytochemistry." (PMID 30717164, 2019).
asthma (1 paper, 2022). "Mice lacking methionine sulfoxide reductase A had increased apoptosis, cardiac dysfunction, and a higher death rate under oxidative stress than did WT mice, and methionine sulfoxide reductase A KO mice have increased atrial fibrillation and asthma." (PMID 36220393, 2022).
bacteremia (1 paper, 2018). "In this regard, our findings showed that CC5 in addition to hla and msrA genes were more frequently present in strains causing osteoarticular bacteremia." (PMID 30319561, 2018).
Central Obesity (1 paper, 2011). "In conclusion, we found that several of the central obesity-associated variants in LYPLAL1, NRXN3, MSRA, and TFAP2B associated with metabolic and anthropometric traits among adult Danes." (PMID 21674055, 2011). "In this study we found several associations with quantitative metabolic and anthropometric traits for the central obesity-associated variants in LYPLAL1, NRXN3, MSRA, and TFAP2B." (PMID 21674055, 2011). "The aim of the present study was to investigate central obesity-associated variants in LYPLAL1, NRXN3, MSRA, and TFAP2B for associations with quantitative metabolic traits in a population-based sample of 6,038 adult Danes (The Inter99 study sample)." (PMID 21674055, 2011). "We demonstrate that several of the central obesity-associated variants in LYPLAL1, NRXN3, MSRA, and TFAP2B associate with metabolic and anthropometric traits in Danish adults." (PMID 21674055, 2011).
cholera (1 paper, 2017). "While intestinal or hepatic lipid accumulation has not been explored in cholera, host MsrA and its interaction with luminal MetO may play a role in the osmotic diarrhea of this disease." (PMID 28586382, 2017).
cholestasis (1 paper, 2023). Impairment of the bile flow caused by obstruction within the liver, or outside the liver in the bile duct system. "Interestingly, MSRA-deficiency has been linked to increased acetaminophen-induced liver injury and might therefore explain cholestasis and liver infarction that we observed in the affected neonate." (PMID 37834755, 2023).
cutaneous leishmaniasis (1 paper, 2013). Leishmaniasis affecting the skin. "Unexpectedly, deletion of L. major msrA had no discernable impact on lesion development in the highly susceptible BALB/c mouse model of cutaneous leishmaniasis." (PMID 23437085, 2013).
cyst (1 paper, 2021). A sac-like closed membranous structure that may be empty or contain fluid or amorphous material. "We find aging and lifespan-related genes, serine racemase and MsrA, are enriched in the cyst." (PMID 34132809, 2021).
diabetic cardiomyopathy (1 paper, 2025). Diabetic cardiomyopathy is a disorder of the heart muscle in people with diabetes. "BBR has the ability to improve diabetic cardiomyopathy by increasing the expression of myocardial methionine sulfoxide reductase A (MsrA) and simultaneously inhibiting cardiac CaMKII oxidation." (PMID 40191425, 2025).
esophageal cancer (1 paper, 2015). A primary or metastatic malignant neoplasm involving the esophagus. "LOH and MSI frequencies were evaluated at chromosomal regions known to be frequently altered in sporadic esophageal cancer with particular attention to loci nearby genes involved in DNA double strand break (DSB) or in the oxidative damage repair pathways (i.e. BRCA1, BRCA2, RAD1 and MSRA)." (PMID 25611972, 2015).
gonococcal infections (1 paper, 2019). "The expression of MsrA/B and the cross-reactivity of the MsrA/B antisera was confirmed by Western blot analysis of 20 clinical isolates from mucosal and disseminated gonococcal infections." (PMID 30787927, 2019).
hearing loss (1 paper, 2025). "Among the four paralogs (MSRA, MSRB1, MSRB2, MSRB3), so far, only MSRA and MSRB3 have been associated with hearing loss." (PMID 40827380, 2025).